FBXL7 (F-box and leucine rich repeat protein 7)
Description:
Substrate recognition component of a SCF (SKP1-CUL1-F-box protein) E3 ubiquitin-protein ligase complex. During mitosis, it mediates the ubiquitination and subsequent proteasomal degradation of AURKA, causing mitotic arrest (By similarity). It also regulates mitochondrial function by mediating the ubiquitination and proteasomal degradation of the apoptosis inhibitor BIRC5.
Synonyms: FBL6; FBL7; KIAA0840
Tractability: PROTAC: ubiquitination databases record sites on it.
Gene: Protein-coding gene on chromosome 5 (15,500,180 to 15,939,795, forward strand). Ensembl gene ENSG00000183580.
Subcellular location: Cytoplasm, cytoskeleton, microtubule organizing center, centrosome
Pathways (Reactome):
Cell Cycle: FBXL7 down-regulates AURKA during mitotic entry and in early mitosis
Immune System: Antigen processing: Ubiquitination & Proteasome degradation
Metabolism of proteins: Neddylation
Gene Ontology:
Molecular function: protein binding
Biological process: protein polyubiquitination; SCF-dependent proteasomal ubiquitin-dependent protein catabolic process; G2/M transition of mitotic cell cycle; mitotic cell cycle; protein ubiquitination; regulation of apoptotic process; ubiquitin-dependent protein catabolic process
Cellular component: SCF ubiquitin ligase complex; centrosome; cytosol; ubiquitin ligase complex
Genetic constraint (gnomAD): Loss-of-function variants: 11 observed, 33.62 expected, observed/expected ratio (o/e) 0.33, 90% interval 0.2 to 0.54. The upper end of that interval is the gene's LOEUF score, 0.54, which puts it in group 2 of 6, group 1 being the genes least tolerant of losing a copy. Missense variants: 527 observed, 643.05 expected, observed/expected ratio (o/e) 0.82, 90% interval 0.76 to 0.88. Synonymous variants: 282 observed, 284.42 expected, observed/expected ratio (o/e) 0.99, 90% interval 0.9 to 1.09.
Homologues: Orthologues: chimpanzee FBXL7 (100% identical), macaque FBXL7 (100% identical), rat Fbxl7 (99% identical), mouse Fbxl7 (98% identical), pig FBXL7 (98% identical), rabbit FBXL7 (98% identical), guinea pig FBXL7 (97% identical), tropical clawed frog fbxl7 (93% identical), dog FBXL7 (88% identical), zebrafish fbxl7 (82% identical), Caenorhabditis elegans fbxl-1 (21% identical), Drosophila melanogaster CG9003 (21% identical), and 24 more. Paralogues in human: FBXL2 (21% identical), FBXL20 (21% identical), FBXL13 (21% identical), FBXL6 (19% identical), FBXL14 (19% identical), FBXL5 (19% identical), FBXL16 (18% identical), FBXL17 (18% identical), SKP2 (18% identical), FBXL18 (17% identical), FBXL4 (17% identical), FBXL19 (15% identical), and 3 more.
Diseases named in the same sentence as FBXL7 in open-access papers:
FBXL7 is named in the same sentence as 41 diseases in open-access papers, as found by Europe PMC text mining. Sharing a sentence is not in itself a finding about the gene and the disease. The quoted sentences say what the papers report.
gastric cancer (7 papers, 2017 to 2025). A primary or metastatic malignant neoplasm involving the stomach. "Mechanistically Aurora A activation represses FBXL7 transcriptional expression causing Survivin accumulation, thus contributing to gastric cancer cell growth and resistance to doxorubicin." (PMID 35906197, 2022). "Thus, downregulation of FBXL7 may contribute to the overexpression of Aurora A, which is associated with worse prognosis in gastric cancer." (PMID 35906197, 2022). "Specifically, FOXP1 is recruited to multiple sites within the promoter region of FBXL7 and transactivates the expression of FBXL7 in gastric cancer cells." (PMID 35906197, 2022). "Together, these results suggest that AURKA targets FOXP1 to negatively regulate the expression of FBXL7, which can in turn negatively regulate Survivin protein levels in gastric cancer cells." (PMID 28218735, 2017). "Basal levels of FBXL7 mRNA and protein were low in gastric cancer cells and only became detectable after AURKA depletion." (PMID 28218735, 2017). "Moreover, FBXL7 repression by the Aurora A-FOXP1 axis further suppresses FBXL7-mediated Survivin ubiquitylation and subsequent degradation via proteasome, resulting in drug resistance in gastric cancer cells." (PMID 35906197, 2022). "Furthermore, Aurora-A kinase promotes survivin stability through transcriptional and translational regulation of Fbxl7 expression in gastric cancer." (PMID 32410646, 2020). "Interestingly, Aurora A inhibits FBXL7 transcription in gastric cancer cells." (PMID 35906197, 2022). "Increase of FBXL7, SCF ubiquitin E3 ligase component, induces ubiquitylation and degradation of survivin in gastric cancer." (PMID 29290980, 2017). "It is noteworthy that endogenous FBXL7 mRNA and protein levels were low in AURKA wild-type gastric cancer cells; however, both FBXL7 mRNA and protein levels reached detectable levels only after AURKA depletion." (PMID 28218735, 2017). "Although the exact mechanism regarding how FBXL7 influences ovarian cancer chemoresistance has not yet been well clarified, a study in gastric cancer suggests that FBXL7 adjusts survivin expression through the ubiquitin-proteasome pathway." (PMID 35582023, 2021). "This led us to speculate that FBXL7 was a potential tumor suppressor gene and its expression was repressed by AURKA in gastric cancer." (PMID 28218735, 2017).
asthma (6 papers, 2015 to 2024). "SNPs within GLCCI1, T gene, and ALLC were associated with changes in the lung function and rs10044254 SNP within FBXL7 was associated with changes in the asthma symptom scores." (PMID 30647901, 2019). "SNPs within the GLCCI1, T gene, and FBXL7, were associated with ICS response in pediatric asthma populations and were conducted by the same research group." (PMID 30647901, 2019). "In addition to THSD4 and HIVEP2, age-by-genotype interactions also prioritized genes previously identified as asthma candidate genes, including DPP10, HDAC9, TBXAS1, FBXL7, and GSDMB/ORMDL3, as pharmacogenomic loci as well." (PMID 32119686, 2020). "However, in vitro and/or in silico analyses provide additional evidence that genes discovered in these GWAS (e.g. GLCCI1, FBXL7, T gene, ALLC, CMTR1) might play a direct or indirect role in asthma/treatment response pathways." (PMID 30647901, 2019).
breast carcinoma (5 papers, 2012 to 2022). "The single nucleotide polymorphism (SNP) rs12652447 of FBXL7 is relevant to an increased risk of breast cancer in people carrying breast cancer gene 2 (BRCA2) mutations in breast cancer genome-wide association studies." (PMID 35906197, 2022). "Previous studies have demonstrated that a single nucleotide polymorphism (SNP) in FBXL7 showed the strongest associations in BRCA2 mutation carriers of breast cancer." (PMID 30301218, 2018). "E3 Ubiquitin ligase; regulates cell cycle; expression of Fbxl7 variants correlate with increased risk of breast cancer in BRCA2 mutation carriers." (PMID 24255707, 2013). "In addition, integrating pathway and gene information, we identified five (ID4, ANXA4, CXCL9, MYLK, FBXL7) and six (SQLE, E2F1, PTTG1, TSTA3, BUB1B, MAD2L1) known cancer genes significant for ovarian and breast cancer respectively." (PMID 22759382, 2012). "However, silencing FBXL7 had no evident effect on the protein levels of Snail1 in either SW620 colon cancer cells or MCF-7 breast cancer cells, indicating that FBXL7-mediated Snail1 turnover likely occurs in a manner dependent of specific cell context." (PMID 35906197, 2022).
glioma (4 papers, 2020 to 2024). A benign or malignant brain and spinal cord tumor that arises from glial cells (astrocytes, oligodendrocytes, ependymal cells). "miR-152-5p inhibits malignant progression and tumorigenesis by targeting FBXL7, potentiating gliomas’ temozolomide sensitivity." (PMID 37925170, 2023). "The levels of miR-152-5p were gradually downregulated, whereas FBXL7 expression was gradually upregulated with an increase in tumor grade in glioma tissues." (PMID 35906197, 2022). "FBXL7 silencing inhibits proliferation, migration, and invasion of glioma cells and sensitizes glioma cells and ovarian cancer cells resistant to chemotherapeutic drugs." (PMID 35906197, 2022). "Overexpression of FBXL7 almost completely reversed the inhibition of glioma cell proliferation, migration, invasion, and enhanced glioma cell sensitivity to the anti-glioma drug temozolomide by miR-152-5p overexpression." (PMID 35906197, 2022). "The expression of FBXL7 in glioma tissue is significantly up‐regulated, which is related to the poor prognosis and the grade of glioma." (PMID 32150671, 2020). "Overexpression of miR‐152‐5p and knock‐down of FBXL7 in glioma xenograft models enhanced TMZ‐mediated anti‐tumour effect and impeded tumour growth." (PMID 32150671, 2020). "Depletion of FBXL7 or overexpression miR‐152‐5p in U87 cell‐derived glioma xenograft models also enhanced anti‐tumour effect mediated by TMZ." (PMID 32150671, 2020). "We observed that miR‐152‐5p lies upstream of FBXL7 and regulates FBXL7 level and overexpressed miR‐152‐5p repressed glioma development and progression and targets FBXL7 to augment cytotoxicity induced by TMZ in glioma cells." (PMID 32150671, 2020). "Poor survival in cases with higher FBXL7 expression than those with lower levels in the glioma patients was observed on Kaplan‐Meier survival analysis (P < .001)." (PMID 32150671, 2020). "Alternately, overexpressed miR‐152‐5p led to strikingly reduced FBXL7 expression in U87 and U251 cells, and significantly enhanced in cells depleted with miR‐152‐5p, and this relationship was observed in glioma tissues of Grade IV (WHO)." (PMID 32150671, 2020). "TMZ‐induced cytotoxicity, proliferation, migration and invasion in glioma cells were impeded by the knock‐down of FBXL7 or overexpressed miR‐152‐5p." (PMID 32150671, 2020). "Moreover, the levels of miR-152-5p were inversely correlated with FBXL7 levels in advanced glioma tissues." (PMID 35906197, 2022). "FBXL7 mRNA levels gradually increased with increasing glioma grade." (PMID 35906197, 2022). "Moreover, FBXL7 level negatively correlates with the progression and survival of patients with glioma." (PMID 35906197, 2022). "Therefore, the miR-152-5p-FBXL7 axis appears to play a significant role in glioma progression and in the efficacy of chemotherapeutic drugs." (PMID 35906197, 2022). "Furthermore, on analysing Grade IV of glioma samples, the cases with higher FBXL7 expression exhibited a shorter survival compared with those in low expression groups (P < .001)." (PMID 32150671, 2020). "This led us to hypothesize that the anti‐tumour effects of TMZ might be by regulation of miR‐152‐5p/FBXL7 axis in glioma." (PMID 32150671, 2020). "Thus, the miR‐152‐5p suppressed the progression of glioma and associated tumorigenesis, targeted FBXL7 and increased the effect of TMZ‐induced cytotoxicity in glioma cells, further enhancing our knowledge of FBXL7 activity in glioma." (PMID 32150671, 2020). "Therefore, in this study, we examined the function of miR‐152‐5p in regulating the growth and progress of tumours by targeting FBXL7 as well as the function of miR‐152‐5p/FBXL7 axis on cytotoxicity induced by TMZ in glioma." (PMID 32150671, 2020). "Our study investigated the activity of FBXL7 and miR‐152‐5p in glioma." (PMID 32150671, 2020). "In addition, glioma cells exhibited a remarkably up‐regulated FBXL7 level than that in NHAs (normal human astrocytes)." (PMID 32150671, 2020).
glioma (continued). "Also, the combined effect of TMZ, miR‐152‐5p, and FBXL7 on xenograft growth, glioma cell migration, proliferation, invasion and TMZ resistance must be investigated." (PMID 32150671, 2020). "Furthermore, the expression of miR‐152‐5p reduced remarkably in glioma cells and it exerted its activity through targeted FBXL7." (PMID 32150671, 2020). "However, the downstream or upstream regulatory molecules or pathways in gliomas must be explored to assess the molecular basis of the biomarker capacity of FBXL7." (PMID 32150671, 2020). "Taken together, we demonstrate here for the first time a regulatory axis miR‐152‐5p/FBXL7 in glioma tumorigenesis and indicate that FBXL7 and miR‐152‐5p may be a potential treatment target for glioma, singly or combined with TMZ." (PMID 32150671, 2020). "We could also show that knock‐down of FBXL7 improved inhibitory effects mediated by TMZ glioma xenograft growth in vivo and on viability of glioma cell in vitro and that FBXL7 expression was inhibited in glioma cells by miR‐152‐5p via direct interaction." (PMID 32150671, 2020). "Thus, FBXL7 may serve as a biomarker for poor prognosis and may be a therapeutic target for patients with glioma and ovarian cancer, particularly those who have undergone chemotherapy." (PMID 35906197, 2022). "Thus, our findings indicated that FBXL7 is clearly a target of miR‐152‐5p in glioma." (PMID 32150671, 2020). "In addition, how FBXL7 regulates glioma function will be investigated in the future studies." (PMID 32150671, 2020). "The activities of FBXL7, TMZ and miR‐152‐5p were analysed in vivo singly or in combination, on mouse xenografts, in glioma tumorigenesis." (PMID 32150671, 2020). "We further observed that the silencing of FBXL7, TMZ stimulation alone, or overexpression of miR‐152‐5p led to reduced volume and weight of glioma xenograft tumour." (PMID 32150671, 2020). "We could show here after miR‐152‐5p overexpression, the suppression of glioma cell migration, proliferation and invasion, as well as enhanced in vitro TMZ‐triggered decline in glioma cell viability, and these effects were nullified by enhanced FBXL7." (PMID 32150671, 2020).
ovarian carcinoma (4 papers, 2015 to 2022). A malignant neoplasm originating from the surface ovarian epithelium. "FBXL7 plays a prominent role in ovarian cancer survival and its overexpression in ovarian cancer patients is implicated in paclitaxel resistance and poor prognosis." (PMID 35582023, 2021). "Under the condition of overall survival (OS), high levels of FBXL7 transcripts were significantly (p = 0.0017) associated with a poor survival rate and unfavorable hazard ratio (HR = 1.4, p = 0.0018) in ovarian cancer patients." (PMID 30301218, 2018). "Evidence indicates that FBXL7 is associated with an ovarian cancer gene." (PMID 30301218, 2018). "Moreover, our data showed that the fold change of FBXL7 expression post-treatment with PTX was causally correlated with the 50% inhibitory concentrations (IC50) of PTX in a panel of ovarian cancer cell lines." (PMID 30301218, 2018). "A high expression rate of FBXL7 is associated with poor survival of ovarian cancer patients." (PMID 30301218, 2018). "Furthermore, the mRNA levels of FBXL7 in the high-risk cohort were significantly upregulated compared to the low-risk cohort in ovarian cancer patients." (PMID 30301218, 2018). "The data indicated that high levels of FBXL7 transcripts could be an independent factor for predicting an unfavorable risk for cancer recurrence after adjuvant chemotherapy in ovarian cancer patients." (PMID 30301218, 2018). "More importantly, FBXL7 levels are markedly correlated with paclitaxel resistance in ovarian cancer cells." (PMID 35906197, 2022). "Immunohistochemical staining also confirmed that the protein levels of FBXL7 were inversely correlated with the overall survival of ovarian cancer pateints." (PMID 35906197, 2022). "In contrast, in ovarian cancer patients, higher levels of FBXL7 transcripts correlate with worse overall survival and progression-free survival and also predict a higher risk of recurrence after adjuvant chemotherapy." (PMID 35906197, 2022). "In the present study, the mRNA levels of FBXL7 were downregulated in a PTX -sensitive ovarian cancer cell line (OVSAHO) but upregulated in PTX-resistant KURAMOCHI cells treated with PTX." (PMID 30301218, 2018). "Although these data suggest a role for FBXL7 in controlling cell proliferative activity and viability, further studies investigating the relationship between FBXL7 and drug resistance in ovarian cancer are needed." (PMID 30301218, 2018). "The IHC results revealed that high protein levels of FBXL7 refers to a poor overall survival rate and an increased hazard ratio in the enrolled ovarian cancer patients." (PMID 30301218, 2018). "Otherwise, we cannot exclude the interference of enrolled cohort sizes and ovarian cancer types in the prognostic estimation against FBXL7 transcript as we utilized the public databases." (PMID 30301218, 2018). "Our current data indicate that high levels of FBXL7 mRNA indicated a significantly poor PFS compared with low levels of those mRNA in ovarian cancer patients who were in the treated with PTX cohort." (PMID 30301218, 2018). "Furthermore, FBXL7 mRNA levels were positively correlated with the PTX IC50 concentrations of several ovarian cancer cell lines." (PMID 30301218, 2018). "In this study, we found that FBXL7 could serve as a poor prognosis marker in ovarian cancer patients." (PMID 30301218, 2018). "Furthermore, high protein levels of FBXL7 refers to a poor OS and an increased hazard ratio in the enrolled ovarian cancer patients." (PMID 30301218, 2018). "FBXL7 may be a useful biomarker for predicting complete pathologic response in ovarian cancer patients who decide to receive post-operative PTX therapy." (PMID 30301218, 2018). "In summary, FBXL7 upregulation plays a key role in PTX-resistant response in ovarian cancer cells." (PMID 30301218, 2018). "Furthermore, FBXL7 upregulation is positively correlated with IC50 concentrations of PTX in ovarian cancer cell lines." (PMID 30301218, 2018).
ovarian carcinoma (continued). "Besides, we also performed immunohistochemistry (IHC) staining against a tissue microarray composed of various ovarian cancer types to estimate the prognostic significance of FBXL7 protein levels in ovarian cancer patients." (PMID 30301218, 2018). "Therefore, FBXL7 upregulation might play a key role in the mechanism for PTX-resistance in ovarian cancer cells." (PMID 30301218, 2018). "FBXL7 upregulation and pathological stage significantly predicted a poor RFS probability after adjuvant chemotherapy in ovarian cancer." (PMID 30301218, 2018). "To estimate the clinical relevance of DGKH, FBXL7, and MFSD6 in patients with ovarian cancer, we next performed Kaplan-Meier analysis using the K-M Plotter database." (PMID 30301218, 2018). "Under the condition of progression-free survival (PFS) probability, we found that FBXL7 and MFSD6 transcripts at high levels—but DGKH at low levels—significantly (p < 0.05) predicted a poor prognosis in the unclassified ovarian cancer patients." (PMID 30301218, 2018). "In assessments of progression-free survival probability, high levels of FBXL7 transcript strongly predicted a poor prognosis and unfavorable response to PTX-based chemotherapy in patients with ovarian cancer." (PMID 30301218, 2018). "Since FBXL7 showed the strongest significance in both Kaplan-Meier analysis and Cox regression tests, we focused on the investigation of its role in predicting and mediating PTX resistance in ovarian cancer." (PMID 30301218, 2018). "Similarly, in the ovarian cancer patients receiving taxol adjuvant therapy, the elevated mRNA levels detected by probes for DGKH (except probes 235952_at and 240145_at), FBXL7, and MFSD6 appeared to be correlated with poor outcomes." (PMID 30301218, 2018).